NGF (nerve growth factor)
Diseases named in the same sentence as NGF in open-access papers (continued):
Sharing a sentence is not in itself a finding about the gene and the disease.
neurodegenerative disease (continued). "Currently, many neurotrophic factors such as nerve growth factor (NGF) and brain-derived neurotrophic factor (BDNF) have been investigated for treating neurodegenerative diseases such as MS and AD." (PMID 31683745, 2019). "Nerve growth factor (NGF), extensively studied as neuro-protector agent in neurodegenerative diseases, is involved in neuronal survival and reparative processes." (PMID 29334986, 2018). "Since NGF and BDNF play important roles in the development and maintenance of neuron function and survival, the link between these neurotrophic factors and neurodegenerative diseases is unsurprising." (PMID 30223579, 2018). "The roles of NGF and BDNF in neurogenesis also has been researched in some detail, and their potential use as a treatment for neurodegenerative disease has been investigated." (PMID 23536825, 2013). "Therefore, the NGF-potentiating effect of isorhamnetin could be considered as a new direction in developing drugs or health food supplements to help the prevention and recovery of neurodegenerative diseases." (PMID 22761636, 2012). "Additionally, boosting neurotrophic factors like BDNF and nerve growth factor (NGF), alongside immune-modulating agents, offers a comprehensive approach to treating neurodegenerative diseases." (PMID 40869138, 2025). "Neurotrophins are members of the nerve growth factor (NGF) family of proteins that induce the survival and development of neurons and therefore their activation can be an interesting approach to the treatment of neurodegenerative diseases." (PMID 37508002, 2023). "When the levels of CaMkII and AMPK are reduced at the onset of neurodegenerative disease, the consequent reduced ability to express PGC-1α, FNDC5, BDNF, NGF, and GDNF could lead to cognitive dysfunction and deteriorating physical fitness." (PMID 35805580, 2022). "Therefore, a small molecule that mimics or enhances the NGF activity and can pass through BBB can be a promising candidate for treatment of neurodegenerative diseases." (PMID 32831994, 2020). "Combining nerve growth factor (NGF) and quercetin with superparamagnetic IONPs promoted neurite outgrowth and increased the complexity of the neuronal branching trees in PC12 cells, as potential therapeutics for neurodegenerative diseases." (PMID 32184709, 2020). "On the other hand, nerve growth factor (NGF), brain-derived neurotrophic factor (BDNF), neurotrophins like NT-3, NT-4, NT-5, have attracted attention as potential therapeutics for severe neurodegenerative diseases such as AD or as regeneration-promoting compounds." (PMID 32545418, 2020). "In conclusion, BDNF combined with NGF significantly improved NSC neuronal differentiation, which may provide support for the practical application of NSCs in neurodegenerative diseases." (PMID 25051506, 2014). "Thus, NGF and BDNF, or their receptor agonists, have been used to treat AD and other neurodegenerative diseases." (PMID 23651534, 2013). "Discovery of growth factors and their pro-survival effect led to a closer investigation of specific nervous system cytokines - Nerve Growth Factor (NGF), Brain-Derived Nerve Factor (BDNF), Glial-Derived Nerve Factor (GDNF) - involvement in the outcome of neurodegenerative diseases." (PMID 21699711, 2011). "Although the administration of NGF in neurodegenerative disorders has demonstrated efficacy in in vitro studies and animal models, these effects have not been replicated yet in patients with neurodegenerative diseases." (PMID 40153582, 2024). "Panaxydol enhances the expression and secretion of nerve growth factor (NGF) and brain-derived neurotrophic factor (BDNF) in Schwann cells (SCs), improving SC viability and biological characteristics, effectively protecting neurons from degenerative disease damage." (PMID 39193331, 2024).
neurodegenerative disease (continued). "Therefore, spicatoside A regulates NGF and BDNF secretion—the two major neurotrophins that help to maintain neuronal survival and play functionally active roles in the central nervous system of patients with neurodegenerative diseases." (PMID 26075266, 2015). "Neurotrophic factors (NTFs), such as nerve growth factor (NGF), brain-derived neurotrophic factor (BDNF) and glial cell-line derived neurotrophic factor (GDNF), play pivotal roles in neuronal development and survival and exhibit therapeutic potential in animal models of neurodegenerative diseases." (PMID 23923031, 2013). "In this study, we genetically modified adult human OBNS/PC to overexpress human NGF (hNGF) and green fluorescent protein (GFP) genes, which are common genes used to trace engrafted NSCs and to enhance their therapeutic potential against traumatic and neurodegenerative diseases." (PMID 24367504, 2013). "Therefore, the NGF-potentiating effect of ATR volatile oil, α-asarone or β-asarone, could be considered as a new direction in developing drugs or health food supplements to help the prevention and recovery of neurodegenerative diseases in future." (PMID 27685847, 2016).
infection (53 papers, 2005 to 2025). The state of being infected such as from the introduction of a foreign agent such as serum, vaccine, antigenic substance or organism. "Early-life infection by respiratory syncytial virus (RSV) is associated with aberrant expression of the prototypical neurotrophin nerve growth factor (NGF) and its cognate receptors in human bronchial epithelium." (PMID 22272270, 2012). "Knockdown of NGF gene expression by specific siRNA transfection virtually blocked rrRSV replication in bronchial cells pre‐exposed to TiO2‐NP (P < 0.002), suggesting that NGF upregulation by nanoparticles predisposes human airways to more severe subsequent infection by RSV." (PMID 28701524, 2017). "In contrast, bronchial epithelial cells were more susceptible to RSV infection and also showed a significant NGF upregulation subsequent to infection, suggesting that the availability of NGF may affect the efficiency of RSV infection." (PMID 19649262, 2009). "However, nerve sprouting only occurred with serum from horses that were showing signs of infection after transportation and hence the increased NGF activity could have been associated with the inflammatory state of the horse." (PMID 37083137, 2023). "Another mechanism involves the interaction between the secreted N-terminal domain of HSV-2 gG and NGF, leading to higher NGF activity and increased neurite outgrowth, also during infection." (PMID 38275838, 2024). "Studies by Christine Wilcox and Eugene Johnson in the late 1980s showed that removal of NGF was an effective inducer of HSV-1 reactivation in primary neuron infection models they had developed." (PMID 35746680, 2022). "In this research, we found changes in NGF concentration at the same time of infection in immunosuppressed hosts." (PMID 35563321, 2022). "We also observed that the neutralization of NGF prevented the increase in neurite number by 333-TFP-FL infection in all experiments." (PMID 32669337, 2020). "Infection of HEK-293T cells with 333-TFP-FL increased the number of neurites in the presence of NGF compared to the number for mock-infected cells." (PMID 32669337, 2020). "Infection with the HSV-2 MS or 333 strain counteracted the repelling effect of HEK-293T cells in an NGF-dependent manner, having a stronger impact on neurite number than on neurite length." (PMID 32669337, 2020). "Inflammation following tissue injury or infection is characterized by releasing proinflammatory mediators including bradykinin, prostaglandins, nerve growth factors (NGF), proinflammatory cytokines, and chemokines from immune cells." (PMID 33363143, 2020). "Infection increased the NGF concentration in CSF and blood by approximately twofold but the NT3 neurotrophin level was unchanged in CSF and reduced in the blood." (PMID 28975357, 2018). "Here we demonstrate that HSV SgG2 interacts with neurotrophic factors and enhances NGF-dependent growth of FNE to sites of infection probably facilitating transmission to the PNS." (PMID 25611061, 2015). "For example, NGF transcript in T cruzi-infected CFs increases by more than 9-fold at 24-h post-infection (PI) whereas NGF protein in the culture supernatants is boosted by more than 80-fold at 72-h PI." (PMID 23437390, 2013). "Accordingly, our data show that high intracellular levels of miR-221 reduce NGF expression, favor the apoptotic death of infected cells, and limit the infection significantly." (PMID 22272270, 2012). "Previous reports have shown that infection-induced hepatic- and brain granulomas produce NGF, and that enhanced levels of NGF can be detected in granulomatous tissue." (PMID 21059230, 2010). "Throughout the interaction of NGF with these immune cells, NGF induces a chemotactic action, regulating the migration of monocytes and granulocytes to sites of injury or infection, where they contribute to phagocytosis and/or the release of pro-inflammatory biomolecules." (PMID 39596862, 2024).
infection (continued). "As for the involvement of NGF and BDNF in long-lasting symptomatology linked to SARS-CoV-2 contagion, few studies have taken into consideration the cognitive impairment observed after infection." (PMID 39596862, 2024). "In addition, in vivo studies have demonstrated that neutralizing NGF decreased lung inflammation in rats infected with hRSV, protecting against this infection." (PMID 35628626, 2022). "Upon infection of NP-derived cells, we were also able, for the first time, to demonstrate a significant upregulation in NGF and BDNF levels over controls, which indicates that, in vivo, C. acnes has the potential to stimulate neurotrophic factors which trigger neo-innervation." (PMID 33652921, 2021). "Infection with HSV-2 strain 333 increases neurite outgrowth in an NGF-dependent manner." (PMID 32669337, 2020). "However, we cannot formally exclude the possibility that these differences at the amino acid level are relevant to enhance NGF function during infection." (PMID 32669337, 2020). "HSV-2 glycoprotein G and nerve growth factor contribute to this phenotype, which may attract neurites to sites of infection and facilitate virus spread to neurons." (PMID 32669337, 2020). "This suggests that after corneal injury, NGF may promote expression of TLR4 in anticipation of a potential infection." (PMID 30599086, 2019). "Importantly, reactivation was demonstrated as renewed lytic infections in approximately 25% of latently infected cultures when NGF was depleted using antibodies." (PMID 31396173, 2019). "SgG2 seems to bind both chemokines and NGF simultaneously and this property could play a relevant role during in vivo infection due to the contribution of chemokines and neurotrophins in the crosstalk between the immune and nervous system." (PMID 25611061, 2015). "However, while RSV was able to drastically reduce the levels of nerve growth factor (NGF) after 21 days of infection, the level of brain derived neurotrophic factor (BDNF) was not significantly affected in both the treated and untreated groups." (PMID 26693226, 2015). "Although NGF levels were not affected by PbA infection, rosiglitazone treatment was also associated with higher levels of NGF expression on day 11 post-infection." (PMID 24603727, 2014). "However, in the reaction to injury or infection, microglia might overactivate, shifting from their helpful action to focusing on immune defense, which may affect NGF and BDNF availability by promoting neuroinflammation." (PMID 39596862, 2024). "Interestingly, it has been seen that the infection with hRSV in bronchial cells promotes the increment of NGF levels and TrkA, which is the receptor that has a high affinity for NGF, while inducing a decrease of p75NTR, which has a low affinity for NGF." (PMID 35628626, 2022). "Mice infected with RSV are euthanized at consecutive time points post-infection to collect samples and measure the number of inflammatory cells and levels of interferon-gamma (IFN-γ), nerve growth factor (NGF), and brain-derived neurotrophic factor (BDNF)." (PMID 40050867, 2025). "Many cell types secrete nerve growth factor (NGF), the first identified neurotrophic factor that aids in neurite outgrowth, thereby facilitating HSV transmission and infection." (PMID 39207577, 2024). "In this sense, it is possible that the genetic polymorphisms NGF -198C/T and NGF Ala35Val do not influence the levels and functions of NGF in neurological diseases of infectious etiology; therefore, NGF would not contribute to determining the course of infection by HTLV-1 and the development of HAM." (PMID 35746645, 2022). "Following infection or injury, TRPV1 activity is sensitized by various pro-inflammatory mediators such as nerve growth factor (NGF), prostaglandins and bradykinin, which then leads to thermal hyperalgesia." (PMID 33668926, 2021).
infection (continued). "Our results showed that infection of HEK-293T cells with either of two HSV-2 strains reduced the repelling effect of uninfected cells, facilitating neurite outgrowth, in an NGF-dependent manner." (PMID 32669337, 2020). "Most importantly, it was demonstrated that disruption of NGF signaling resulted a renewal of GFP positivity and a spreading infection, indicating renewed lytic replication after a long period of GFP absence." (PMID 31396173, 2019). "As NGF and TrkA are considered downstream targets of KLF7, these results suggested a successful and functional induction of KLF7 by AAV2 infection in spinal cord neurons in vitro." (PMID 28884027, 2017). "To assess neurotrophic factor (NTF) effects on acute replication of HSV1 and HSV2 in adult sensory neurons, we deprived cultured TG neurons of either NGF, GDNF, or NTN during acute infection for 24 h." (PMID 28178213, 2017). "Our study shows for the first time that exposure of human bronchial epithelial cells to nanosized particles prior to infection with RSV increases significantly the efficiency of viral replication, and this effect requires upregulation of the NGF/TrkA axis." (PMID 28701524, 2017). "NGF is expressed in the mucosa and the skin, common sites of HSV replication during primary and recurrent infection." (PMID 27576911, 2016). "AdRas12V infection induced IL-1β expression more significantly than H2O2 treatment, whereas both treatments induced comparable mRNA and protein expression levels of NGF." (PMID 24198727, 2013). "Homogenous neuron cultures are maintained in the presence of nerve growth factor (NGF) and HSV-1 latency can be established with wild type virus by infection in the presence of acyclovir (ACV)." (PMID 22383875, 2012). "HSV-2 gG also enhances NGF-mediated neurite outgrowth during infection, by inhibiting the repulsion that some non-neuronal cells have on neurite outgrowth." (PMID 38275838, 2024). "In the present pilot study, we aimed to identify NGF and BDNF changes in the serum of a small cohort of male and female adolescents that contracted the infection during the second wave of the pandemic (between September and October 2020), notably in the absence of available vaccines." (PMID 35626317, 2022). "This was associated with the decreased expression in mRNA of BDNF, NGF, and FGF2, and elevated expression of IL-1β in the hippocampus at 6 h post infection, but with no changes in optical intensity of the microglia and astrocytes." (PMID 35741412, 2022). "It has been demonstrated that infection with the influenza virus could decrease the levels of BDNF and NGF in the hippocampal region." (PMID 35628626, 2022). "Whether the changes in NGF and BDNF levels in milk from mothers with infection influence their infant’s development remains to be investigated." (PMID 33917718, 2021). "In the absence of infection, however, NGF did not overcome the repulsion mediated by HEK-293T cells." (PMID 32669337, 2020). "Following establishment of latency (without ACV), reactivation was initiated two weeks post-infection by removal of NGF from the culture medium and adding anti-NGF antibodies." (PMID 30691086, 2019). "Among them, at least 65% of the DE genes in PRRSV-infected PAMs at 24 hours post-infection had down-regulation roles in five pathways, including signaling by MAPK (85%), NGF (70%) and GPCR (67%), GPCR ligand binding (67%) and positive regulation of signal transduction (65%)." (PMID 23527143, 2013). "Additionally it was found that BDV CRP4 infection of PC12 cells activates the ERK1/2 pathway, hindering NGF-induced cell differentiation." (PMID 23805250, 2013). "Moreover, boosting NGF and BDNF levels may have neuroprotective actions in infections with high neuroinflammatory mechanisms, such as HIV-associated neurocognitive disorders." (PMID 39596862, 2024).
infection (continued). "The use of serum-free culture media supplemented with NGF as the only growth factor may thus have favored the long-term nonproductive infection of neurons observed in the present study." (PMID 22589716, 2012). "The results demonstrated that the production of NGF did not change significantly after infection, while the expression of p75NTR decreased in both strains, suggesting that the neurotrophic loss could occur due to the deficiency of p75NTR instead of the deficiency of the ligand NGF." (PMID 32696914, 2020).